H2AX (H2A.X variant histone)
Diseases named in the same sentence as H2AX in open-access papers (continued):
Sharing a sentence is not in itself a finding about the gene and the disease.
melanoma (continued). "cAMP signaling was recently reported to decrease Luperox (tert-butyl hydroperoxide, a stable form of hydrogen peroxide)-induced DNA damage measured by γ-H2AX analysis and alkaline comet assay in melanoma cells, implying a stimulatory effect of cAMP signaling in DNA damage repair, including DSB16." (PMID 32879366, 2020). "Moreover, combined treatment approximately doubled the level of phosphorylated γ-H2AX in both melanoma cell lines in comparison to cells treated with either drug alone." (PMID 27705909, 2016). "To this end, we compared the levels of the phosphorylated form of histone H2AX (γ-H2AX) in control and MGRN1-KO human melanoma cells using an immunocytochemical technique." (PMID 35892921, 2022). "As expected, U2AF2 knockdown in melanoma lines led to an increase in sensitivity to TMZ, increased γ‐H2AX levels and decreased HR efficiency." (PMID 34709752, 2021). "In WM793 melanoma cells, induction of DSBs following γ-irradiation (γ-IR; 1 h, 8 Gy) resulted in induction of foci positive for the DSB biomarker γ-H2AX." (PMID 32824412, 2020). "Apoptosis in melanoma cells induced by TMZ and fotemustine was accompanied by double-strand break (DSB) formation (as determined by H2AX phosphorylation) and caspase-3 and -7 activation as well as PARP cleavage." (PMID 19127257, 2009). "Phosphorylation of histone H2AX on serine 139 (γ-H2AX), which was upregulated in those S63845-treated melanoma cell populations that displayed high percentages of Annexin V-positive cells suggests that apoptosis induced by the MCL-1 inhibitor was accompanied with the DNA damage." (PMID 37835493, 2023). "Melanoma cells treated with ADA produced increased levels of DNA damage marker, Υ-H2AX." (PMID 35875119, 2022). "MGRN1-KO cells presented significantly higher levels of γ-H2AX labeling compared with control cells, pointing to a higher burden of DSBs in human melanoma cells lacking MGRN1." (PMID 35892921, 2022). "Furthermore, TOPK binds with and phosphorylates histone H2AX, which suppresses As3+-induced apoptosis in melanoma cells, and TOPK silencing reduces the number of γ-H2AX foci in MCF-7 cells following UV-induced DNA damage." (PMID 34066486, 2021). "Likewise, in A375 melanoma cells, immunoblot analysis revealed rapid onset of D2O-induced stress response phospho-protein modulation (involving downregulation of p-AKT and upregulation of p-ERK, p-JNK, p-eIF2α and p-H2AX)." (PMID 33546433, 2021). "To investigate the percentage of DNA damage within melanoma cells by the SN and RONS generated by CAP we performed a novel DNA damage study by evaluating γ-H2AX which binds specifically to DNA damage site using flow cytometry and immunocytochemistry (ICC)." (PMID 31126298, 2019).
ovarian carcinoma (33 papers, 2011 to 2026). A malignant neoplasm originating from the surface ovarian epithelium. "The association study was informative but there is scope for expansion both in terms of number of cases and scope of analysis, studying prevalence for specific mutations for H2AX, as well looking into whether this gene is methylated in ovarian cancer." (PMID 32887437, 2020). "However, little is known about the expression and role of γ-H2Ax in circulating ovarian cancer-associated cells (CC) from blood (‘liquid biopsies’), although evidence of γ-H2AX expression exists in CC from Stage IV breast cancer patients undergoing platinum therapy." (PMID 34572083, 2021). "To evaluate if CoCl2 induced DNA damage, we exposed primary ovarian cancer cells to a range of CoCl2 concentrations (50, 100, 150 and 200 μM) for 48 h and examined the expression of γ-H2AX." (PMID 36879003, 2023). "In this small cohort of enriched liquid biopsies, it was evident that BRCAm ovarian cancer patients undergoing chemotherapy had more positive γ-H2AX cells (mean 12.3/100 cells) compared with BRCA wt patients (mean 1.7/100 cells)." (PMID 34572083, 2021). "For example, miR-138 suppressed cell proliferation, invasion and migration as a tumor suppressor gene in cervical cancer by targeting H2AX, and in ovarian cancer cells via SOX4." (PMID 33919449, 2021). "Following in silico analysis of H2AX in terms of concomitant gene expression and survival predictions, we explored the expression of H2AX protein in 100 cores of ovarian cancer patients and adjacent tissue." (PMID 32887437, 2020). "qRT-PCR in a small cohort of stage III ovarian cancer patients confirmed higher expression of H2AX when compared to age matched controls." (PMID 32887437, 2020). "MK-2206 in combination with a hemiasterlin derivative (R)(R)(S)-BF65 was previously reported to induce γ-H2AX, an indicator of DNA damage, in ovarian cancer cells." (PMID 31780937, 2019). "Earlier study has also shown the sensitivity of ovarian cancer cells towards high ROS leading to DNA damage as marked by increased phosphorylation of γH2AX (H2A histone family, member X)." (PMID 28881798, 2017). "We therefore examined the levels of γ-H2AX in PJ-34 treated ovarian cancer cells." (PMID 29684820, 2018). "In clear contrast, dual ATM/ATR inhibition strongly potentiates the activity of both ETs against human cervical and ovarian carcinoma cells by efficiently blocking the formation of γ-H2AX, MDC1, BRCA1 and Rad51 foci following ET-exposure thereby resulting in extensive chromosome damage." (PMID 27029031, 2016). "However, the clinical relevance of H2AX in ovarian cancer (OC) remains to be elucidated." (PMID 32887437, 2020). "Immunofluorescence staining revealed that inhibition of KLF5 reduced RAD51 foci and increased γ‐H2AX foci, suggesting that KLF5 plays a crucial role in regulating HRR in ovarian cancer cells." (PMID 37702443, 2023). "In CaOV3, an ovarian cancer line, PRMT5 inhibition decreased markers of both HR and NHEJ, despite an increase in H2AX." (PMID 37596538, 2023). "We found that high RAD21 expression significantly reduced the accumulation of PARP inhibitor-induced γ-H2AX foci, suggesting that RAD21 affected the response of ovarian cancer cells to PARP inhibitors by participating in the DNA damage repair." (PMID 35860572, 2022). "ARN-3261-induced DNA damage and apoptosis were measured with γ-H2AX accumulation, comet assays, and annexin V. ARN-3261 inhibited growth of eight ovarian cancer cell lines at an IC50 of 0.8 to 3.5 μM." (PMID 33503955, 2021). "Expression of H2AX (or H2AFX) was significantly upregulated in the primary and recurrent ovarian cancer when compared to normal tissues in TCGA." (PMID 32887437, 2020).
ovarian carcinoma (continued). "Finally, we explored the clinical utility of γ-H2AX as a pharmacodynamic biomarker, in blood samples from BRCA mutant (n = 3) and BRCA wild type (n = 3) ovarian cancer patients." (PMID 34572083, 2021). "As carboplatin induces apoptosis, we examined whether treatment with ARN-3261 increases carboplatin-induced γ-H2AX punctae in OVCAR8, SKOv3 and OC316 ovarian cancer cell lines." (PMID 33503955, 2021). "In addition, levels of IGFBP7, PAI-1, lamin B1, P21, P27, P62, p-H2AX, and other factors related to cell senescence were significantly elevated, indicating that S1PR1 may be involved in regulating ovarian cancer senescence." (PMID 37828220, 2023). "ALDH1A1-knockdown induced DNA damage, evidenced by robust induction of γ-H2AX and BAX mediated apoptosis, with significant increases in BRCA1 expression, suggesting ALDH1A1-dependent regulation of cell cycle checkpoints and DNA repair networks in ovarian cancer stem-like cells." (PMID 25216266, 2014). "To evaluate whether the knockdown of RAD21 sensitized ovarian cancer cells to PARP inhibitors by impairing DNA damage repair, we treated siRNA- or lentivirus-transfected cells with PARP inhibitors for 4 days at IC50 concentrations and quantified DSB formation based on the presence of γ-H2AX foci." (PMID 35860572, 2022). "In conclusion, we have confirmed that PARP1 is essential for HR in ovarian cancer cell lines lacking BRCA2 and treatment with rucaparib, a PARP inhibitor, increases the formation of γ-H2AX foci." (PMID 34572083, 2021). "Stable NF1 knockdown ovarian cancer models showed that NF1 depletion did not affect basal proliferation but increased sensitivity to hydroxyurea-induced replication stress, accompanied by increased γH2AX accumulation." (PMID 42158468, 2026).
prostate carcinoma (29 papers, 2011 to 2026). A carcinoma that arises from epithelial cells of the prostate gland. "In this study, we compared physician- and patient-reported toxicity in long-term prostate cancer survivors after radiotherapy, and we determined the correlation with a presumable risk factor for late toxicity: γ-H2AX foci decay ratio (FDR)." (PMID 35406443, 2022). "Although expected to operate independently of cancer site and normal tissue type, the γ-H2AX assay’s ability to predict late radiation toxicity via the γ-FDR metric has not yet been examined in patient groups other than those with prostate cancer." (PMID 39223539, 2024). "In a previous study in prostate cancer patients, the γ-H2AX foci decay ratio (γ-FDR) was the strongest predictor of late radiation toxicity." (PMID 39223539, 2024). "BRD4 inhibition resulted in enhanced phosphorylated H2AX in prostate cancer cells because BRD4 is required for the repair of DNA DSBs induced by ionizing radiation." (PMID 33803654, 2021). "Among the possible mechanisms, AA has been proposed to repress H2AX expression in prostate cancer cells or to reduce the expression of anti-apoptotic proteins associated with cell survival and radioresistance in pituitary adenoma cells." (PMID 30774779, 2019). "Whole blood samples were collected from prostate cancer patients before, and at 30 min (for γ-H2AX studies), and 18–24 h (for microarray studies) after the first fraction of irradiation." (PMID 24435511, 2014). "To this end, we assessed DNA damage, through scoring of γ-H2AX foci, and performed whole genome analysis followed by qRT-PCR validation on whole blood samples collected from prostate cancer patients undergoing IMRT." (PMID 24435511, 2014). "Using γ-H2AX and global genome expression analysis, we studied the biological responses induced by low doses of ionizing radiation in prostate cancer patients following IMRT." (PMID 24435511, 2014). "DU-145 prostate cancer cells were treated with a chemical library ±IR and assayed for persistence of γ-H2AX using an automated 96-well immunocytochemistry assay at 4 hours after treatment." (PMID 22768044, 2012). "We have also tested the significance of correlations between γ-H2AX foci and exposure to environmental stressors such as irradiation treatment for prostate cancer, chronic hypoxia (as found in sleep apnea) and vitamin D deficiency." (PMID 23029205, 2012). "We screened 14,400 compounds in 480 mixtures of 30 compounds for the specific phenotype of increased γ-H2AX in DU-145 prostate cancer cells at 4 hours after drug therapy alone or in combination with 2 Gy of radiation." (PMID 22768044, 2012). "Lymphocytes of patients receiving irradiation for the treatment of prostate cancer have been analyzed by scoring gamma-H2AX foci." (PMID 21649920, 2011). "Recently, we found that a less efficient repair of DNA double-strand breaks (DSBs) in ex vivo irradiated lymphocytes, as quantified by the γ-H2AX foci decay ratio (FDR), is an independent risk factor for the development of CTCAE grade ≥ 2 late toxicity in prostate cancer patients treated with EBRT." (PMID 35406443, 2022). "Furthermore, this study confirmed that the anti-PSMA antibody functionalized PSMA-targeting GNPs are effective radiosensitizers for prostate cancer cells through a clonogenic assay and γ-H2AX assay." (PMID 36558293, 2022). "Consistent with this notion, depletion of E2F1 and E2F2 by RNA interference in the PC3 prostate cancer cell line significantly raised the percentage of Serine 139-phosphorylated histone H2AX (γH2AX)-positive cells, indicative of an increased DNA damage signaling." (PMID 36230876, 2022). "Concomitantly, a marked increase in the phosphorylation of H2AX foci was also noticed in MALAT1-silenced DU145 and PC3 cells, indicating the crucial role of MALAT1 in modulating the expression of several HR genes as well as genome integrity in both HR-proficient and -deficient prostate cancer cells." (PMID 37812088, 2023).
prostate carcinoma (continued). "The effect of esomeprazole on DNA damage is in line with an earlier study that reported induction of γ-H2AX by another PPI, pantoprazole, in prostate cancer cells co-treated with docetaxel." (PMID 34262645, 2021). "In the current study, we used the γ-H2AX + 53BP1 DSB focus assay to investigate the time- and dose-dependency of DNA DSB induction and repair in blood leucocytes of prostate cancer patients during their first therapy with 177Lu-PSMA." (PMID 31028426, 2019). "YM155 inhibits the survivin promoter and also induces direct DNA damage as measured by induction of gamma-H2AX and pKAP-1 expression in PC3 prostate cancer cells." (PMID 27050416, 2016). "Previously, it was shown that the natural compound, resveratrol, which inhibits complex I of the ETC, sensitized radioresistant prostate cancer cells by increasing ATM phosphorylation and its target protein γ-H2AX, resulting in cell cycle arrest and subsequently cell death." (PMID 39404412, 2024). "Our prostate cancer patients who were previously treated in the past with IR had a sizeable increase of 44% of γ-H2AX foci/cell over those with no known IR treatment, but these results did not achieve statistical significance (p = 0.23)." (PMID 23029205, 2012). "Finally, we show that dual inhibition of CDK12/13 results in excessive phosphorylation of the DNA damage H2AX in prostate cancer cells but not in our CDK12/13 inhibitor-resistant model system." (PMID 41896195, 2026). "Indeed, treatment of prostate cancer cells with the highly specific CDK9 inhibitor NVP2, or a structurally unrelated CDK9 inhibitor AT7519, induced accumulation of the DNA damage response marker p-H2AX." (PMID 35164752, 2022). "Indeed, combined treatment of prostate cancer cells with OGT inhibitor and the CDK9 inhibitor NVP2 induced the accumulation of p-H2AX in PC and CRPC cells but not in the normal prostate cells." (PMID 35164752, 2022).
osteosarcoma (26 papers, 2008 to 2025). A usually aggressive malignant bone-forming mesenchymal neoplasm, predominantly affecting adolescents and young adults. "For instance, Sam68 expression was shown essential to robust induction of histone variant H2AX phosphorylation (gH2AX) and efficient repair of DNA double-strand breaks (DSBs) in human osteosarcoma cells upon g-irradiation." (PMID 37792222, 2024). "In this study, our results revealed that olaparib induced more severe clustered DNA damage in irradiated osteosarcoma cells, rendering γ‐H2AX/53BP1 foci to be larger and more irregularly shaped relative to irradiation alone." (PMID 38213724, 2024). "In Sam68-deficient conditions, the phosphorylation of ATM, one of the kinases phosphorylating H2AX, as well as its substrates Chk1 and Chk2, is lower than in Sam68-sufficient osteosarcoma cells in response to g-irradiation-induced DSBs." (PMID 37792222, 2024). "Similar to osteosarcoma cells, we observed a significant rise in intracellular ROS and γ-H2AX levels induced by narasin treatment in osteoblast cells as well." (PMID 37864240, 2023). "Western blot analysis of γ-H2AX, a core histone protein that is phosphorylated in response to DNA damage, was increased, suggesting oxidative DNA damage in osteosarcoma cells after narasin treatment." (PMID 37864240, 2023). "Further study revealed that hinokitiol exposure caused cell cycle arrest at the S phase and a DNA damage response with the induction of γ-H2AX foci in both osteosarcoma cell lines." (PMID 35163553, 2022). "MiR-328-3p was reported to increase the radiosensitivity of osteosarcoma cells, inhibit the proliferation, and promote apoptosis through H2AX." (PMID 35087570, 2021). "In addition, TF3 increased the levels of phosphorylated histone H2Ax, Bax, Bak1, and cytochrome c, while reducing the levels of Mcl-1 and survivin in osteosarcoma cells." (PMID 40535821, 2025). "After 12 hours of irradiation, many γ‐H2AX/53BP1 foci were retained in the combined group than in the irradiation group, suggesting that olaparib delayed DNA damage repair and reduced kinetics in irradiated osteosarcoma cells." (PMID 38213724, 2024). "Based on the hypothesis that PARPi may induce DNA damage in irradiated osteosarcoma cells, we monitored the formation of γ‐H2AX foci and 53BP1 foci post-irradiation." (PMID 38213724, 2024). "Based on the hypothesis that PARPi may induce DNA damage in irradiated osteosarcoma cells, we monitored the formation of γ‐H2AX foci and 53BP1 foci within 2 hours and 12 hours post-irradiation." (PMID 38213724, 2024). "U2OS (osteosarcoma cell line) cells transduced for 24 h with Nanoblades programmed with a sgRNA targeting rDNA display the typical γ-H2AX distribution at the nucleolar periphery with RNA Pol I, indicative of rDNA breaks, whilst cells transduced with Nanoblades with control sgRNAs do not." (PMID 30604748, 2019). "In addition, it has been reported that miR-328-3p enhanced the radiosensitivity, inhibited the proliferation and promoted apoptosis in osteosarcoma cells under radiation conditions by directly targeting H2AX." (PMID 31043859, 2019). "Moreover, olaparib induces more γ‐H2AX/53BP1 foci in irradiated osteosarcoma cells (p < 0.05)." (PMID 38213724, 2024). "Herein, it is important to highlight the potency of intact ZR2002 in this aggressive osteosarcoma model, with evidence of intratumoral inhibition of EGFR and apparent DNA damage, as detected via H2AX." (PMID 36980255, 2023).
osteosarcoma (continued). "A report by showed increased C-12 ion-induced cell killing and apoptosis, along with higher expression of p21 and γ-H2AX and proportions of G2/M-phase arrested cells, in KHOS-24S osteosarcoma and A-204 rhabdomyosarcoma cells pretreated with 0.5–1 μM SAHA." (PMID 34513712, 2021). "To validate NEK9 as a RSR protein, we examined for phosphorylation of H2AX Ser139 (γH2AX), an early marker for DNA damage, following NEK9 knockdown in U2OS human osteosarcoma cells." (PMID 25217585, 2014). "In accordance with the data obtained from MCF7 cells, increased phosphorylation of H2AX, blockage of DNA replication indicated by reduced EdU incorporation was also evident in U2OS and Saos-2 osteosarcoma cell lines treated with 11 μM and higher concentrations of compound AF615." (PMID 35548337, 2022). "To test whether DNA replication stress can induce soluble H2AX, we used the human osteosarcoma cell line U-2 OS that, unlike GIST cells, does not depend on a single oncogenically activated tyrosine kinase such as KIT and has bona fide normal DNA damage response pathways." (PMID 18616816, 2008). "On the other hand, TXT2 and TXT4 failed to induce DNA damage in the ALT-positive osteosarcoma U2OS cells, which in turn were characterized by a remarkable accumulation of γ-H2AX upon exposure to MTX, whereas equitoxic amounts of all compounds failed to elicit DNA damage in TERT-negative NHBE cells." (PMID 36437244, 2022).